YAP1 (Yes1 associated transcriptional regulator)
Diseases named in the same sentence as YAP1 in open-access papers (continued):
Sharing a sentence is not in itself a finding about the gene and the disease.
tumor (continued). "Verteporfin is able to inhibit YAP1/TAZ-TEAD activity, cancer stem cell markers’ expression and the tumoursphere in GC, which allows tumour growth inhibition both in vitro and in vivo." (PMID 36615513, 2022). "The results showed that increased CDC42, CDH2, ERBB2, JAG1, YAP1, and YWHAZ were found in the tumor tissues." (PMID 35340237, 2022). "This simple screening assay was uniformly predictive of dependency on YAP1-TEAD for growth and tumor cell invasiveness in cell lines." (PMID 36476495, 2022). "We found that elevated levels of YAP1 and FAPα in stromal fibroblasts were significantly correlated with NPC tumor fibrosis and poorer metastasis-free survival." (PMID 35986369, 2022). "In diffuse-type GC, activation of the YAP1 signaling induced by KRT17-mediated cytoskeletal reorganization elevated the IL-6 level, further accelerating EMT for tumor metastasis." (PMID 36289774, 2022). "YAP1 is closely correlated with epithelial–mesenchymal transition (EMT), stemness of cell, organ size, regeneration, and tumor progression." (PMID 35672802, 2022). "Phosphorylation of MST1 and LATS2 promoted by metallothionein 2A (MT2A) restrained the YAP1 nuclear localization, thereby preventing CRC from enhanced tumor growth and liver metastasis." (PMID 36289774, 2022). "From the diagnosis and prognosis aspects, the decreased expression of Hippo kinases and increased YAP1 and TAZ within tumor tissues serve as indicators for clinical outcomes of GI cancer patients." (PMID 36289774, 2022). "To investigate if IGF-IR signaling pathway effectors and YAP1 are co-regulated in MLS development, we analyzed the expression of IGF-II, IGF-IR, and YAP1 in tumor specimens from 54 MLS patients using IHC." (PMID 35459264, 2022). "Esophageal cancer (EC): EC cell lines and human EC samples often express constitutively active YAP1 and TAZ, which is significantly correlated with poor survival and adverse clinicopathological features such as histological classification and tumor stage." (PMID 36289774, 2022). "In this study, we employ multi-omics approaches based on bulk and single-cell transcriptomic datasets to investigate the role of MAP2K1, mTOR, YAP1 and EGFR in the tumor immune context of tumor microenvironment." (PMID 35655775, 2022). "LD2, a novel GRK3 inhibitor, actively reduced tumor cell growth, invasion, and tumor sphere formation in vitro in multiple GAC cell models and in vivo in a GAC PDX model with high GRK3 and YAP1 expression." (PMID 35996148, 2022). "Moreover, YAP1 may recruit the CAFs and MDSCs to tumor site to suppress the immune response." (PMID 36479120, 2022). "An array-based analysis revealed in the second tumor an amplicon at 5q11.2 including MAP3K1 gene and the second one at 11q22.2 containing genes: YAP1 and BIRC2/3, known for its anti-apoptosis function, allowing a comprehensive view of cancer progression." (PMID 35246108, 2022). "In addition, the nuclear localization of YAP1 was increased in various cancer tissues and the regulation of YAP1 translocation between the cytoplasm and nucleus is a key step in hippo signaling, which is critical for physiological cell proliferation, organ size and tumor development." (PMID 36532767, 2022). "In the past years, accumulating evidence has focused on the causal relationship between irregular activation of the Hippo pathway, particularly YAP1 and TAZ, and tumor occurrence in numerous cancer types." (PMID 36289774, 2022). "OTUB2 regulated the protein expression of YAP1/TAZ to promote cell proliferation, migration, invasion, and tumor development." (PMID 35850645, 2022). "More importantly, in vivo xenograft assays also revealed that LIN28A-enhanced tumor growth and pulmonary localization were dependent on LIN28/MSI2-mediated YAP1 activation." (PMID 35102250, 2022). "LncBRM, together with YAP1 targets, is highly expressed in HCC cells, and the expression level increases with tumor severity." (PMID 35672802, 2022).
tumor (continued). "Upon dysregulation, YAP1 and TAZ have also been illustrated to possess the tumor-facilitating potentials that contribute to tumor initiation and progression." (PMID 36289774, 2022). "Overall the CRISPR data indicate that the 11q22.2 amplification residing genes YAP1, TMEM123, BIRC2-3 are essential for VU1365-T tumor cells vitality." (PMID 34997070, 2022). "YAP1 overexpression, as well as Wnt overexpression, is required for RSPO2-induced tumor initiation and progression." (PMID 35672802, 2022). "Analysis of TCGA datasets via the R2 platform also showed that YAP1 and TIAM1 expression exhibited a positive correlation (R > 0.1, p < 0.01) in almost 30% of all tumor patterns (12 out of 34)." (PMID 35773411, 2022). "Ubiquitin-specific peptidase 10 (USP10) was reported to interact with YAP1 and TAZ to suppress their ubiquitination, resulting in accelerated HCC tumor growth." (PMID 36289774, 2022). "Numerous studies have shown that upregulation of YAP1 can induce epithelial–mesenchymal transformation (EMT), inhibit apoptosis and promote the production of tumor stem cells." (PMID 35350840, 2022). "In this model, exosomes increase FAPα levels and activate YAP1 signaling to promote CAF-mediated effects, including fibrosis and tumor growth, while concurrently inducing an immunosuppressive TME that benefits NPC progression." (PMID 35986369, 2022). "In the present study, tumors with YAP1 positivity, low TILs, and high TSR showed significantly higher tumor stiffness than those with YAP1 negativity, high TILs, and low TSR." (PMID 36291755, 2022). "Collectively, these results demonstrate that SNHG16 can promote tumor growth, metastasis, and MCTC generation and that YAP1 can rescue the effect of SNHG16 on tumor progression." (PMID 36147462, 2022). "These signatures allow for quantitative assessment of YAP1/TAZ activity and have, in part, been applied to identify tumor entities that display high YAP1/TAZ activity in larger cancer patient cohorts." (PMID 35798875, 2022). "When OTUB2 is overexpressed, it can directly stabilize and bind to YAP1/TAZ through SUMO, activate the YAP1/TAZ expression and activating downstream target genes such as CTGF and CYR61 to promote the proliferation, invasion and metastasis of tumor cells." (PMID 35850645, 2022). "In line with this, expression levels of YAP1 and WWTR1 as well as their target genes CTGF and CYR61 were significantly decreased in ER+ BRCA relative to their non-tumour tissues." (PMID 35217640, 2022). "Expression levels of ZEB1, YAP1, CCND1, and BCL2 were consistent with the database analysis and demonstrated significantly high values in tumor tissues (logFC ≥ 1.5)." (PMID 35453574, 2022). "Emerging evidences revealed that YAP1 also took the center stage in cancers, by which to regulate the CSC self-renewal and tumor cell behaviors." (PMID 35102250, 2022). "Previously, we and others have reported that Hippo/YAP1 mediates CSC attributes and tumor progression through regulation of its downstream targets, such as SOX9, Birc5, and Cyr61." (PMID 35996148, 2022). "While YAP1 shRNA induction was associated with 62% and 72% knockdown of YAP1 mRNA 24 h and 96 h post doxycycline supplementation, respectively, 6 days post doxycycline removal, 41% inhibition of YAP1 mRNA was still present, possibly explaining the absence of tumor regrowth observed." (PMID 35689194, 2022). "Since we originally identified Robo3s induction in murine tumor cells surviving chemotherapy, and since Hippo signaling has been connected to drug resistance, we hypothesized that ROBO3s expression could support tumor cell resistance by stimulating YAP1 activity." (PMID 36057630, 2022).
tumor (continued). "Paired targeted next-generation sequencing analysis of tumor and matched normal sample was negative for somatic mutations as well as structural variants, and revealed a relatively flat DNA copy number profile with focal genomic gains and losses at chromosome 11q including the YAP1 locus." (PMID 35986430, 2022). "These gain‐ and loss‐of‐function experiments in vitro and analysis of available human tumor datasets suggest a functional relationship between HES1, YAP1, and CDKN1C in FN‐RMS, with both HES1 and YAP1 upstream of CDKN1C." (PMID 36037042, 2022). "Instead, extracellular components, including LIF, CCL2, PDGFA, Hippo/YAP1, as well as, immune responses and angiogenesis, might pivotally participate in development of intratumor heterogeneity through remodeling methylome and transcriptome of tumor foci from same mGBM patients." (PMID 34987659, 2022). "It is also notable that although the recruitment effect of YAP1 depends on the interaction of CCL2 and its receptor CCR2 on TAMs, other CCR2+ cells have the opposite effect, which is tumor suppression." (PMID 35672802, 2022). "To evaluate the anti-tumor activity of LD2 in vivo, we used GA0518 patient-derived PC cells which have high GRK3 and YAP1 expression." (PMID 35996148, 2022). "The hippo tumor suppressor pathway includes the MST1/2‐LATS1/2 kinases cascade, which phosphorylates YAP1 and segregates YAP1 in the cytosol for degradation." (PMID 34003553, 2021). "In summary, the following marker genes were used for subsequent analysis in supratentorial tumours: RELA, ELL3, FBP2, PCP4L1, and MYO3A for detection of RELA+ tumours; and MRAP, IGF1, CAPS, and WWC1 for detection of YAP1+ tumours." (PMID 34314101, 2021). "This group has shown that inhibition of Src activity using dasatinib was accompanied by a reduction in YAP1/TAZ activity, tumor growth and metastasis." (PMID 34693980, 2021). "In conclusion, our study provided evidence for the first time that PWAR6 exerts tumour suppressor activity in human PDAC cells by interacting with EZH2 and facilitating its repression of YAP1, thus mediating proliferation, apoptosis and metastasis of PDAC." (PMID 33834618, 2021). "Based on genomic datasets, the expression profiles of candidate genes in CCA cases were analyzed using GEO databases and the increasing levels of feasible tumor markers including HMGB1, SOX9, and YAP1 in patients with CCA." (PMID 35201494, 2021). "To explore the mechanism of circRNAs-YAP1 in EMT, we analyzed the circRNA expression profiles in6 pairs of CRC tissues and adjacent non-tumor tissues and paid attention to the function and regulation mechanism of circ1662." (PMID 33754062, 2021). "In addition, YAP1 promotes resistance to chemotherapy, targeted therapy, and hormone therapy through the upregulation of several pro-survival and antiapoptotic genes, and they also influence responses to immunotherapy by modulating the tumor immune microenvironment." (PMID 33420363, 2021). "Through the upregulation of SLC7A5, YAP1/TAZ are able to increase mTORC1 activity and tumor proliferation and survival." (PMID 33953707, 2021). "Partial knockdown of YAP1/TAZ in mice injected with active Src (SrcY527F) expressing A375 cells, resulted in a reduction of Src mediated tumor growth and metastasis and extended mouse survival." (PMID 34693980, 2021). "TFAP2C upregulates the GPX4 gene in tumor cells and regulates some ferroptosis regulators, such as epidermal growth factor receptor (EGFR), CDKN1A, and YAP1, thereby negatively regulating ferroptosis." (PMID 34804126, 2021). "Binding of YAP1/TEAD4 to ERα-bound enhancers is required for the induction of ERα target genes and tumor growth." (PMID 34145394, 2021). "Exosomes containing MALAT1 are released into the tumor microenvironment, inhibiting and depleting YAP1, activating ERK1/2 signal transduction, and enhancing the expression of MMP2 and MMP9, thereby promoting tumor invasion and metastasis." (PMID 35145971, 2021).
tumor (continued). "YAP1 has also been shown to promote adaptive resistance to anti-PD1 therapy, and the YAP1/TAZ target gene signature has been shown to correlate with tumor immune cell infiltration in patient samples." (PMID 34685695, 2021). "Tumor stromal cells, particularly CAFs, are among the main modulator of EMT and stemness through the induction of YAP1 and secretion of various cytokines." (PMID 34680267, 2021). "To explore the mechanism of circRNAs-YAP1 in EMT, we also analyzed the circRNA expression profiles of the 6 pairs of CRC tissues and adjacent non-tumor tissues by high-throughput sequencing." (PMID 33754062, 2021). "High nuclear YAP1 expression was still a significant determinant of decreased DMFS after adjustment for hormone receptor status, tumor size, and nuclear YAP1 expression by the Cox proportional hazards model (HR 1.893, 95% CIs 1.009–3.552, P = 0.047)." (PMID 33718163, 2021). "Decreased miR-375 subsequently resulted in upregulation of oncogenes YAP1 and SP1 promoting the tumor progression." (PMID 33814008, 2021). "According to their study, PTEN-null GBMs promote the recruitment of macrophage through the YAP1-LOX-β1 integrain-PYK2 axis, thus contributing the hostile tumor microenvironment (TME) reflected by poor prognosis." (PMID 33828082, 2021). "In gastric cancer, YAP1/TAZ acts as an oncogene and promotes tumor formation by co-transcription with the TEAD transcription factor." (PMID 34368119, 2021). "miR-641 has been reported to be a tumor-suppressive miRNA by targeting various downstream genes, including ZEB1, HOXA9, MDM2, and YAP1." (PMID 34603448, 2021). "We also examined the effects of HNK on YAP1 and TEAD1 expression in the tumor tissues from the AOM/DSS treated mice." (PMID 34206989, 2021). "Kras and YAP1 converge at the transcription factor FOS, activating a transcriptional program which regulates the epithelial-mesenchymal transition (EMT) and tumour survival." (PMID 33613118, 2021). "The YAP1 S127A mutant, which escapes negative regulation by LATS kinases, is more effective at inducing tumor and has been used in many cancer models." (PMID 34150758, 2021). "This was further supported by Western blot analyses on infigratinib‐resistant tumours, where there was an increase in CSC markers such as SOX9, YAP1 and DLK1 particularly in the later stages of resistance." (PMID 33179425, 2021). "In examining the dissected tumor tissues, both dipyridamole and GW4869 decreased protein contents in cyclin D1, β-catenin, YAP1, Runx2, phosphorylated Smad2/3, HMGB1, RAGE, and CD42b, except the TLR4." (PMID 33669632, 2021). "The Hippo core complex controls the transport of YAP1/TAZ proteins to the nucleus, and abnormal upregulation of YAP1/TAZ expression or their nuclear localization occurs in SCC, which promotes tumor progression and metastasis." (PMID 34421348, 2021). "It is becoming clear that YAP1 and TAZ are multifaceted regulators of the processes driving tumor growth." (PMID 34685695, 2021). "Analysis of mRNA levels from the CCLE database showed that the expressions of YAP (YAP1) and TAZ (WWTR1) were upregulated in KRAS-mutant lung cancer cells, compared to KRAS wild-type tumor cells." (PMID 34073318, 2021). "Furthermore, NF2 deletions are also found in other tumor types such as renal cell carcinoma, cervical squamous cell carcinoma, schwannomas and meningiomas, which may hence respond equally well to the inhibition of YAP1 activation." (PMID 34685695, 2021). "The majority of supratentorial tumours contain oncogenic fusions between the genes C11orf95 and RELA (C11orf95–RELA) or YAP1 (YAP1‐MAMLD1)." (PMID 34314101, 2021). "High cytoplasmic YAP1 expression and low YAP1 NCR were found to be independent risk factors for CRC prognosis in multivariate Cox analysis (after correcting confounding variables), above results indicated that cytoplasmic YAP1 may be used as an indicator for staging of tumor." (PMID 33240680, 2020).
tumor (continued). "Hyper-activation of YAP1/TAZ also leads to the dysregulation of other pathways involved in proliferation and tumor growth." (PMID 32722184, 2020). "YAP1 and LINC00152 were highly expressed in 83 cases CRC tissues compared with matched para‐tumor tissues, meanwhile, LINC00152 expression was positively correlated with YAP1 level." (PMID 32042551, 2020). "Subsequently, we verified that TEAD1, a transcriptional coactivator of Yes-associated protein 1 (YAP1), directly bound to the HIF1A promoter region and the YAP1 and TEAD1 proteins co-regulated the expression of HIF1A, thus promoting tumour glycolysis." (PMID 33218358, 2020). "Emerging evidence demonstrate that YAP1 and WWTR1 have distinct roles where they partner with different transcription factors, drive different downstream effectors and also modulate the tumor microenvironment distinctively." (PMID 32990596, 2020). "Using immunofluorescence, we found that YAP1 downstream effectors identified in mRNA analysis, ANKRD1, AMOTL2 and AXL were increased in LATS1/2 cKO tumours." (PMID 32404936, 2020). "As the role of linc-OIP5 in the upstream of YAP1/Notch signaling was confirmed by this study, antiangiogenic therapies targeting linc-OIP5 will be meaningful for tumor resistance and metastasis." (PMID 32046779, 2020). "Co-administration of MGC-803-derived xenografts with VP (a YAP1 inhibitor) and AZD4547 exerted a synergetic effect on tumor growth inhibition." (PMID 32934314, 2020). "The YAP1 protein expression level is canonically regulated by the LATS1/2 kinase of the Hippo pathway and is critical for tumor initiation, progression, and metastasis." (PMID 33489890, 2020). "In sarcoma and prostatic adenocarcinoma, CAFs secrete TGF-β, IL-6 and tumor necrosis factor-alpha (TNF-α) that activate YAP1/TAZ and NFκB signaling in tumor cells, resulting in inhibition of tumor cell proliferation." (PMID 33114328, 2020). "To identify a clinical useful YAP1 inhibitor, we took advantage of BET bromodomain inhibitors (e.g., JQ1) that has been in clinical trials for many tumor types and proven safe." (PMID 32175692, 2020). "Our study confirm the importance of Hippo core pathway member YAP1, but also of upstream effector NF2 for the regulation of tumor morphology and invasive properties." (PMID 31959902, 2020). "Here, the authors show that YAP1 activation upon alectinib treatment leads to therapy resistance and that inhibiting both YAP1 and ALK leads to longer tumor remission in mice." (PMID 31900393, 2020). "Histological analysis revealed that the expression of YAP1, TAZ and vimentin was higher and the expression of E‐cadherin was reduced in the tumour tissues of hyperglycaemic mice (P < .05)." (PMID 32678516, 2020). "YAP1/STAT3 complex regulates ANG-2 expression, promoting angiogenesis in the postnatal retina and tumor tissues." (PMID 32722184, 2020). "Deletion of YAP1’s negative regulators LATS1 and LATS2 kinases in NEX-Cre lineage in double conditional knockout mice also generates similar tumours, which are rescued by deletion of YAP1 and its paralog TAZ." (PMID 32404936, 2020). "We also found that nicotine enhanced expression levels of YAP1 and HIF1A in a dose-dependent manner, both of which induce EMT and tumor growth in PDAC cells in vitro and in murine xenograft models." (PMID 32894161, 2020). "The results revealed that YAP1 is directly connected to secreted AREG, CTGF, CYR61, FGF1 and MSLN that are involved in fibrosis and other key signaling pathways involved in the tumor-stroma interactions." (PMID 32054505, 2020). "We defined the optimal overexpression threshold for YAP1 and TAZ by ROC analysis for every case based on the progression endpoint, and the cutoff was established at 20% of tumor cells." (PMID 32365528, 2020).